MTOR (mechanistic target of rapamycin kinase)
Diseases named in the same sentence as MTOR in open-access papers (continued):
Sharing a sentence is not in itself a finding about the gene and the disease.
tumor (continued). "As energy sensors, AMPK and mTOR are closely related to autophagy and apoptosis of tumor cells." (PMID 35745143, 2022). "GSVA of the KEGG pathways revealed that the immune-related pathways, such as the T cell receptor pathway, were enriched in patients with low VARS1 expression, while tumor growth pathways such as the cell cycle pathway and the mTOR pathway were enriched in patients with high VARS1 expression." (PMID 36303162, 2022). "Whether growth relevant AKT/mTOR is involved in regulating tumor cell adhesion and migration and how adhesion/migration relevant integrins may alter tumor growth and proliferation was also explored." (PMID 35626034, 2022). "Klotho is a tumor suppressor that has previously been shown to interact with the mTOR pathway." (PMID 36220392, 2022). "We show co-occurrence of amplifications in MYC and genes from the PI3K pathway in HGSOC and other CIN-driver tumours and that inhibition of the activated mTOR survival pathway in the context of MYC-amplified tumours should be considered in future clinical trials." (PMID 36289203, 2022). "This could indicate a higher proliferation status of LEAD since TSC2 is a known tumor suppressor acting mainly by inhibiting mTOR signaling." (PMID 35743538, 2022). "In conclusion, our experiments indicated that SLC6A14 was upregulated and could activate the Akt-mTOR signaling pathway, thereby promoting the tumor progression of CRC." (PMID 35907820, 2022). "Interestingly, the mTOR inhibitor rapamycin has anti-tumor activity and induces a BCG-mediated immune response." (PMID 36397350, 2022). "NAP1L1 may contribute to the aggressive nature of tumor cells through the PI3K/AKT/mTOR signaling pathway in lung AC." (PMID 35351053, 2022). "FBXW7 is a tumor suppressor gene encoding a subunit of the Skip1–Cull–F–box (SCF) ubiquitin ligase complex, which controls proteasome–mediated degradation of various cell cycle regulators such as cyclin E, c–Myc, Notch1, and mTOR." (PMID 36497403, 2022). "Furthermore, in pleural mesothelioma, VER-155008 inhibits HSP70 by inducing G1 cell cycle arrest and disrupting the PI3K/AKT/mTOR pathway, thereby suppressing tumor proliferation." (PMID 36036010, 2022). "KD did not appear to be able to provide the same level of mTOR inhibition required to cause tumor regression." (PMID 35685742, 2022). "mTOR promotes AR receptor phosphorylation and activates AR transcription in a ligand-independent manner, and inhibition of mTOR reduces protein translation and prevents abnormal cell proliferation and tumor angiogenesis." (PMID 35886904, 2022). "In summary, our findings suggest that LDOC1 may have tumor-suppressive effects by inhibiting AKT/mTOR activation in HCC." (PMID 35957693, 2022). "The mTOR pathway affects tumor metabolism through multiple approaches." (PMID 35557985, 2022). "However, mTOR inhibition simultaneously upregulates PD-L1 expression in some circumstances such as in xenografted tumour tissues and in RCC cell lines." (PMID 36577970, 2022). "Generally, mTOR inhibitors may have an anti-tumor effect via stimulating the extrinsic apoptotic pathway." (PMID 35402264, 2022). "In cancer, abnormally activated Akt/mTOR signaling is of paramount importance, allowing tumor cells to grow independently of exogenous growth stimuli, maximizing nutrient uptake and influencing metabolic plasticity and contributing to multidrug resistance mechanisms." (PMID 36139434, 2022). "Furthermore, we found that TMAO upregulates POSTN and activates the ILK/AKT/mTOR pathway, which induces tumor proliferation and migration." (PMID 35676936, 2022).
tumor (continued). "Likewise, the promotion of autophagy was found to inhibit tumor cell growth in a breast cancer study via the inhibition of MAPK-regulated mTOR activity, and the phosphorylation of ERK was hindered." (PMID 35860020, 2022). "In addition, ADAMTS9 has been identified to inhibit tumor progression by regulating the PI3K/AKT/mTOR pathway." (PMID 35574388, 2022). "Our results indicate that the downregulation of IFNAR promotes the activation of PI3K-Akt/mTOR, which is related to the immunosuppressive function of G-MDSCs and we further clarifies the specific mechanism by which tumor conditions induce immune activation to tilt toward immunosuppression." (PMID 35013108, 2022). "Moreover, the extracellular acidosis would present an inhibition on mTOR signaling pathway, interfering anti-tumor effects of natural NK." (PMID 35646923, 2022). "Western blotting detected changes in the transfection pathway, and it was found that the AKT/mTOR pathway was inhibited upon overexpression of miR-197-3p, which might be related to the inhibition of tumor progression." (PMID 35342334, 2022). "The role of dioscin in autophagy is well studied, but most studies conducted on various tumour cell lines indicated dioscin exerts activities through PI3k/Akt-dependent or mTOR-dependent pathways and reported that the autophagy induced by dioscin is usually caused cell death." (PMID 35566180, 2022). "Our study provides an accurate guide for the use of mTOR inhibitors in patients with BLCA tumours." (PMID 36312898, 2022). "Indeed, we found that apoptin affects the energy metabolism of tumor cells by targeting PKM2 and by affecting the AMPK/mTOR pathway resulting in cell death of tumor cells." (PMID 36284386, 2022). "Also, KEGG pathway results revealed that EFNAs were implicated in numerous tumor-related classical pathways including: the “PI3K-Akt signaling pathway”, “mTOR signaling pathway”, “MAPK signaling pathway” and “Ras signaling pathway”." (PMID 35945523, 2022). "In addition, PI3K/AKT/mTOR signal transduction also plays a significant role in tumour metastasis via the induction of tumour EMT and angiogenesis." (PMID 35883139, 2022). "AZD8055 inhibits tumor progression in PTC by affecting mTOR activity." (PMID 35692574, 2022). "Since mTOR is a major downstream target of AKT, inhibition of the AKT/mTOR pathway could possibly trigger autophagy in tumor cells." (PMID 35186488, 2022). "Everolimus inhibits the mTOR pathway, resulting in blockade of cell growth and tumor progression." (PMID 35805003, 2022). "Therefore, targeting PI3K/Akt/mTOR‐mediated autophagy has emerged as a possible tumour therapeutic strategy." (PMID 35106915, 2022). "Previous studies have shown that activation of mTOR promotes tumor growth and metastasis." (PMID 35655161, 2022). "Moreover, the CCN proteins were associated with hypoxia, ROS production, mTOR, extracellular matrix organization, EMT, angiogenesis, autophagy and apoptosis by analyzing hallmarks of tumor, GO and KEGG." (PMID 36589241, 2022). "Previous studies have shown that STK25 could suppress tumor cell growth and proliferation by downregulating the Golph3-dependent mTOR pathway, promoting tumor cell apoptosis by regulating CCM2TrkA, etc.." (PMID 35756606, 2022). "Akt-mTOR inactivation was observed as well in OS xenograft tumor tissues after SKI-V injection." (PMID 35115496, 2022). "It has been shown that activation of the PI3K/Akt/mTOR pathway is connected to tumor aggressiveness through the regulation of multiple cellular pathways, including the induction of CSC and EMT phenotypes, which may also be increased in many tumors." (PMID 35681259, 2022). "Importantly, Akt-mTOR activation was significantly inhibited in SKI-V-treated pCCa-1 tumor tissues, as the levels of phosphorylated Akt1 and S6K were dramatically decreased." (PMID 35541904, 2022).
tumor (continued). "In addition, reverse signaling mediated by PD-L1 further promotes tumor growth by enhancing glycolytic metabolism in PD-L1+ tumor cells via the Akt/mTOR pathway." (PMID 35236415, 2022). "The mTOR signalling-related pathway also plays a vital role in tumour occurrence and progression." (PMID 36294896, 2022). "Inhibition of mTOR and S6K may increase PI3K/Akt signaling, which may enhance carcinogenesis and alter tumor susceptibility to some other chemotherapeutic treatments." (PMID 36109789, 2022). "Among several surrogate markers assessing mTOR inhibition in skin, peripheral blood mononuclear cells, and/or in the tumor cells, a decrease in the p-S6K has been reported as the most reliable pharmacodynamical biomarker in preclinical studies and clinical trials." (PMID 36139669, 2022). "However, the biology of the protein is unclear, with early evidence linking HIF-1α mediated EMT in hypoxia and the PI3K/AKT/mTOR pathway with AHNAK2 as possible modes to increase tumour proliferation, migration, and survival." (PMID 35158796, 2022). "Surprisingly, we found a downregulation rather than an upregulation of several Src kinase and Src kinase-related family members—i.e., B-lymphoid tyrosine kinase (BLK), lymphocyte-specific protein tyrosine kinase (LCK) and Fyn-related kinase (FRK)—in the AKT/mTOR-inhibitor-resistant tumor cells." (PMID 35454789, 2022). "Mammalian target of rapamycin (mTOR) inhibitors have yielded promising results in post-transplant-related EBV-SMT, and some congenital immunodeficiency-associated EBV-SMTs showed tumor control after bone marrow transplantation." (PMID 35141174, 2022). "Growth arrest and apoptosis occurred in the tumor cells by suppressing Akt/mTOR signaling." (PMID 35847860, 2022). "Notably, tumor-related signaling pathways such as PI3K, MYC, mTOR, and Wnt were significantly enriched in high-risk group, and continuous activation of these pathways have been demonstrated to be linked with HCC." (PMID 35711939, 2022). "Moreover, exosomes released from hypoxia-treated tumor cells facilitate M2 macrophage polarization in infiltrating myeloid cells through the microRNA let-7a and Akt-mTOR signaling pathway." (PMID 35669852, 2022). "mTOR, GβL, and Raptor constitute an important signaling pathway in the regulation of tumor growth." (PMID 35907820, 2022). "Similarly, S100A10 activated mTOR pathway by interacting with annexin A2 to accelerate tumor aerobic glycolysis, promoted malignant proliferation, and suppressed cell apoptosis in gastric cancer." (PMID 36072431, 2022). "The results suggest that tumor mutation, not the cfDNA mutation in mTOR pathway, mainly contribute to the immune stimuli in tumor micro-environment and promote the ICI treatment sensitivity in turn." (PMID 35642038, 2022). "In addition, the Akt/mTOR pathway is one of the classic signaling pathways to mediate tumor metabolic homeostasis, which is beneficial for tumor growth and metastasis." (PMID 35454801, 2022). "It is noteworthy that radon radiation could increase p-PI3K, p-AKT, and p-mTOR levels, and the anti-tumor effect is accompanied by the inhibition of the PI3K/AKT/mTOR pathway." (PMID 35485300, 2022). "Furthermore, activation of p38 MAPK in response to nutritional stress induces ATF6α-dependent upregulation of mTOR signaling, resulting in dormancy and subsequent survival of tumor cells." (PMID 36436127, 2022). "In addition to genetic alterations leading to stable oncogenicity to promote oncogenesis and chemotherapy resistance, the production of proteins and expression of mRNA in PI3K/AKT/mTOR signaling pathways also participate in neoplasm growth." (PMID 36539659, 2022).
tumor (continued). "In addition, pancreatic CSCs can be inhibited by metformin directly through the mTOR pathway, in which it blocks tumor growth by suppressing neoplastic proliferation, resulting in malignant cell apoptosis." (PMID 35454306, 2022). "Resveratrol induces autophagy by directly inhibiting mTOR through ATP competition, which may be related to its excellent anti-tumor effect." (PMID 36091810, 2022). "The HER2 receptor is a member of the ErbB family of transmembrane tyrosine kinase receptors, and its dimerization catalytically activates its downstream signaling cascades through the MEK/ERK/MAPK and PI3K/AKT/mTOR pathways and mediates tumor angiogenesis by activating the VEGF signaling pathway." (PMID 36031613, 2022). "Thus, AMPK-mediated PROX1 phosphorylation dictates BCAA metabolism and mTOR signalling to limit glucose consumption, possibly facilitating tumour cell adaptation to metabolic stresses." (PMID 36433955, 2022). "In addition to that, we were able to demonstrate that combined targeting of AKT and mTOR significantly decreases tumor burden in our orthotopic xenograft mouse model after transplantation into the left liver lobe." (PMID 35454789, 2022). "We try to explain the result in this way: The proliferation and development of CAFs are regulated by PI3K/AKT/mTOR signaling pathway, and CAFs might promote tumor progress via IGF1R/AKT1/mTOR pathway in tumor microenvironment." (PMID 35768785, 2022). "mTOR has critical roles in tumor progression, and mTOR complex 1 (mTORC1), is composed of mTOR bind to Raptor, GβL, and DEPTOR and could be inhibited by FDA approved drug Rapamycin." (PMID 35690832, 2022). "Through the inhibition of the PI3K/Akt/mTOR signaling pathways, toosendanin could inhibit the growth of glioma cells and tumor growth in vivo animal models." (PMID 36408249, 2022). "Furthermore, blockage of mTOR signaling in tumor cells with the inhibitor rapamycin dramatically reversed the inhibition on cell proliferation and growth and prevented senescence induction in MCF7 and HCT116 tumor cells induced by SCT and CA." (PMID 34747157, 2022). "And the mTOR inhibitors everolimus and sirolimus could suppress cell proliferation and tumor growth in animal models of HCC." (PMID 35433409, 2022). "Treatment with inhibitors of the PI3K/mTOR pathway significantly reduced tumor growth rates, whereas an inhibitor of the proteasome showed only modest effect depending on tumor size, and inhibitors of histone deacetylases and DNA topoisomerase produced no tumor response in this model." (PMID 35070081, 2022). "Finally, continuous delivery of the potent mTOR inhibitor rapamycin resulted in reduced growth of tumours derived from engrafted Leprctrl PDV cells." (PMID 36450983, 2022). "Inhibiting the mTOR signalling pathway by rapamycin attenuated the tumour-promoting effect of UCK2." (PMID 36447138, 2022). "While, for the established SCC, only mTOR inhibition in combined with other therapy, e.g., radiotherapy can yield positive effects in inducing tumor regression, highlighting the temporal regulation of mTOR on tumor development and the importance of time window for the administration." (PMID 35938153, 2022). "We speculate that EGFR-TKIs and PD-1/PD-L1 inhibitors block PI3K/AKT/mTOR signaling, which blocks the absorption of essential amino acids by tumor cells, resulting in increased phenylalanine, n-acetyl-l-leucine, and n-acetyl-d-tryptophan." (PMID 36034789, 2022). "It has also been proven that the PI3K/Akt/mTOR pathway plays a key role in tumor angiogenesis." (PMID 35681715, 2022). "The consistent relationship identified between MTOR mutations and MSI suggests that MTOR may represent a marker for the prediction of MSI status and tumor immunogenicity." (PMID 35883111, 2022). "After adjusting tumor purity, the expression of ALOX12B was negatively associated with IGFR1, AKT1, MTOR, and EIF4EBP1, and the same correlation could also be observed in SPRR1A." (PMID 35768785, 2022).
tumor (continued). "However, while sirolimus is effective against various TSC-based tumor lesions, this allosteric mTOR inhibitor is primarily cytostatic, and tumors regrow upon cessation of therapy." (PMID 35359406, 2022). "Similarly, another phase I trial documented the significant efficacy of hydroxychloroquine in combination with mTOR inhibitor temsirolimus in tumor suppression." (PMID 36160153, 2022). "Lastly, it was stated that LAGE3 might promote tumor development in HCC via PI3K/AKT/mTOR and Ras/RAF/MAPK pathways." (PMID 35313850, 2022). "Tumours with a high pattern of invasion were less likely to have a high p-mTOR extent score." (PMID 35883491, 2022). "Our omics analysis of clinical data from cohorts of NSCLC revealed that dysregulation of EGFR/MAP2K1/MTOR/YAP1 signaling pathways are associated with disease progression, anticancer drug resistance, tumor immune infiltration, immune-invasive phenotypes and worse prognosis of the cohorts." (PMID 35655775, 2022). "This may be reflective of the poor outcomes of sarcopenic patients or possibly an effect of increased visceral adiposity on tumor responsiveness to mammalian target of rapamycin (mTOR) inhibition." (PMID 36422290, 2022). "Furthermore, PD-L1 on cancer cells induces the glycolytic process through Akt/mTOR signaling, inducing an immunosuppressive tumor microenvironment." (PMID 35565420, 2022). "In addition, mammalian target of rapamycin (mTOR), a multi-tumor therapeutic target, was also evaluated." (PMID 36057262, 2022). "Spatial visualization of fatty acids showed that C16:1 and C18:1 accumulate obviously in tumor tissue and that C16:1 may promote EC cell invasion and metastasis through mTOR signaling." (PMID 36227107, 2022). "mTOR contributes to redox homeostasis, a vital component of neoplasia." (PMID 35216092, 2022). "Furthermore, ATM‐associated DNA damage response (DDR) cooperated with MAPK and mTOR signaling pathways to control citrate‐induced tumor cell growth arrest and senescence." (PMID 34747157, 2022). "PI3K/AKT/mTOR signaling activation is one of the crucial features of this tumor group." (PMID 36158697, 2022). "SLC6A14 was upregulated in CRC and could promote tumor progression by activating the Akt-mTOR signaling pathway, which may serve as an effective molecular target for the treatment of CRC." (PMID 35907820, 2022). "Additionally, miRNA can participate in regulating the proliferation, apoptosis, metastasis, autophagy and other biological processes of tumor cells, via mediating the mTOR signal pathway." (PMID 35844793, 2022). "The mTOR pathway plays a key role in controlling the cell cycle and tumor growth." (PMID 35805003, 2022). "Therefore, the cAMP and mTOR pathways can upregulate cell cycle progression, cell mobility, cell survival, and metastasis in several tumourous tissue types." (PMID 35563045, 2022). "Additionally, tumor cells can be protected by various forms of stress via autophagy, which can be triggered by mTOR inhibition." (PMID 36077374, 2022). "Therefore, miRNAs that regulate the PI3K/AKT/mTOR signalling pathway play an important role in regulating the drug resistance of tumour cells." (PMID 35883139, 2022). "This difference in signaling between the two models could be explained by H2O2-driven deregulation in the mTOR pathways in TPC tumor model." (PMID 35269445, 2022). "The solid LUAD-enriched PI3K/AKT/mTOR and c-Myc signaling, could be enhanced by ubiquitination modifications in tumor cells." (PMID 36138435, 2022).